SOX2 (SRY-box transcription factor 2)
Diseases named in the same sentence as SOX2 in open-access papers (continued):
Sharing a sentence is not in itself a finding about the gene and the disease.
cancer (continued). "Regarding genetic instability, the genes SOX2, OCT3/4, c-MYC, and KLF4—commonly used for reprogramming somatic cells to iPSCs—are often expressed at higher levels in various cancer cells and are involved in the development and progression of several cancers." (PMID 40541178, 2025). "Furthermore, our study demonstrates that circ_0000467 promotes cancer stem cell (CSC) characteristics, as evidenced by increased spheroid formation and elevated levels of CSC markers (CD24, CD44, EpCAM, SOX2, and Nanog)." (PMID 40290725, 2025). "In addition, BAZ1A complexes with SOX2 to drive the enhancer-promoter interaction and facilitate the recruitment of BRD4, thereby activating the expressions of cancer stem cells (CSCs)-related signature." (PMID 40204721, 2025). "Indeed, multiple studies have suggested an inverse correlation between the expression of SOX2 and SOX9 in cancer in a context dependent manner." (PMID 38275880, 2024). "These cancer cells that have undergone EMT become more invasive and metastatic due to the presence of self-renewal EMT-mediating transcription factors such as Snail, Zebi, SOX2, KLF4, and many others which were discussed extensively before." (PMID 39403386, 2024). "Notably, among the 14 TFs whose binding sites were sex-dependently enriched across different cancers, eight were previously found to be enriched among sex-biased expressed genes, including SP1, ETV1, ELF1, E2F1, CREB1, CTCF, SIX2, and SOX2." (PMID 39716176, 2024). "Our study showed that PP reduced the levels of Sox2, c‐Myc and TBX3, suggesting that it may inhibit the clonogenic potential of PDAC cells by targeting these cancer stemness markers." (PMID 39632282, 2024). "Previous studies have determined a direct role for the SS18-SSX fusion protein in regulating expression of several cancer-related genes, such as EGR1, FOS, IGF2, FZD10, SOX2, UNCX and CDH4." (PMID 39045458, 2024). "In addition to CD44, Nanog Homeobox (Nanog), SRY (Sex Determining Region Y)-Box 2 (SOX2), and Octamer-Binding Transcription Factor 4 (Oct4) play crucial roles in maintaining cancer stemness progression and the poor prognoses in cancer patients." (PMID 38612715, 2024). "Likewise, OCT4 and SOX2 have been discerned to interact collaboratively with EMT transcription factors, thereby intensifying cancer cells’ plasticity and stem-like attributes." (PMID 39403386, 2024). "Furthermore, the high CBLL1 expression observed in the tumourspheres was accompanied by the upregulation of other established cancer stem cell markers, including LGR5, NANOG, SOX2, KLF4 and c-MYC mRNA levels." (PMID 38339195, 2024). "Stemness, known as the self-renewal capacity of cancer stem cells, is regulated by many signaling pathways, including TGF-β, Hedgehog, Wnt, Notch, and FGF, and transcription factors, including NANOG, OCT4, SOX2, KLF4, and c-MYC." (PMID 39516821, 2024). "Thus, we also examined expression levels of HNSCC specific cancer stem cell (CSC) markers, CD44 and ALDH, as well as other markers for HNSCC stemness, SOX2, NANOG, and BMI1." (PMID 38435825, 2024). "Moreover, downregulated cancer stemness proteins, including BMI1, c-MYC, and SOX2, were observed in EXOSC5 knockdown EC cells." (PMID 38164180, 2024). "CSCs are defined as cancer cells that exhibit certain characteristics of embryonic stem cells, which give rise to the entire set of cell types from a single cell and high expression of OCT4, SOX2 and so forth stemness markers." (PMID 38775844, 2024). "DATS could be inhibiting the cancer stemness of HNSCC cells by decreasing the expression of stemness-related genes Oct4 and SOX2." (PMID 38254868, 2024). "To demonstrate that the beneficial effect of iPSC-based cancer vaccines can be enhanced by radiotherapy, we generated mouse iPSCs from BALB/c fibroblasts and verified them by two well-known iPSC markers, Oct4 and Sox2." (PMID 38821980, 2024).
cancer (continued). "Alone or in cooperation with other signalling pathways, NF-κB promotes the expression of a wide variety of downstream targets, including stem factors (NANOG, SOX2, CD44, and others) and microRNAs, like let-7 and microRNA-21, contributing to self-renewal and expansion features of cancer stem cells." (PMID 38612718, 2024). "In this study, only a few stemness genes, such as SOX2, TWIST1, and CD34, were aberrantly expressed [absolute fold change (FC) ≥ 2] in more than five cancer types, indicating that integrins may function downstream of key stemness factors." (PMID 39436262, 2024). "Our finding that the expression levels of KRT-14, SOX2, CD44, and ALDH1a decreased upon si-m/hVDAC1-B BC treatment suggests that the metabolic reprogramming of cancer cells via VDAC1 depletion reduces CSC markers, suggesting the inhibition of their proliferation and/or induction of differentiation." (PMID 38607066, 2024). "SOX2 and SOX9 are often deregulated in cancer and a dual role was described for both TFs." (PMID 38275880, 2024). "We then looked at the transcript levels of these genes and found that, consistent with the protein levels, the transcription of Notch1, Sox2, and the stem cell marker Aldh1a3 genes were suppressed, while that of Numb was elevated, in response to RAB4A knockdown in RAB4A-high cancer cells." (PMID 39463384, 2024). "Additionally, OCT4 overexpression in cancer stem cells increases the expression of Notch, SRY-Box transcription factor 2 (Sox2) and Nanog, which are crucial for stem cell proliferation and differentiation." (PMID 39633710, 2024). "SOX2 expression was significantly increased in the presence of M0, M1, or M2-like macrophages and carboplatin compared with their same condition vehicle and in presence of M0 (PBMC-derived) or M1 (THP1) compared with cancer cells alone with carboplatin." (PMID 39287565, 2024). "In addition, the phosphorylation of aPKC was significantly correlated with the expression of Gli1, PARD3 and Sox2 (R > 0.4), emphasizing the important role of aPKC in mediating PARD3, SHH signalling and cancer stemness." (PMID 38317186, 2024). "Additionally, to evaluate the effect of HNF4A on the stemness of the spheroids, we screened for expression of cancer stem cell markers, including CD24, CD44, NESTIN, OCT4, and SOX2." (PMID 39165427, 2024). "Finally, the pan-cancer analysis of primary pediatric tumors illustrates the potential clinical relevance of ZNF555 targeting mesenchymal cancers and SOX2-related cancers." (PMID 39009887, 2024). "In fact, studies indicate that HIF stimulates the expression of stem cell markers like OCT4, SOX2, NANOG, MYC, and miR-302 in cancer cells, implying that hypoxic niches may have a significant role in transforming non-cancer stem cells into cancer stem cells." (PMID 39201332, 2024). "Mechanistically, NSDHL knockdown impaired the cancer stemness characteristics of BCSCs by suppressing TGF-β signaling, which in turn decreased the secretion of TGF-β 1 and TGF-β3, inactivated Smad2 and Smad3, and downregulated the expression of SOX2 and NANOG, key regulators of cancer stemness." (PMID 39516821, 2024). "SOX2 was reported to activate autophagy by transcriptionally promoting Beclin1 expression, thereby upregulating EMT-related genes and promoting sphere enrichment and cancer progression." (PMID 37639070, 2023). "Together with NANOG and SOX2, OCT3/4 is widely regarded as marker of cancer stem cells, and higher expression of OCT3/4 has been proven to indicate worse clinical outcomes in most cancer types, i.e., more aggressive tumors, short overall survival and chemoresistance." (PMID 37476834, 2023). "Similarly, SOX2 controls cell proliferation and is commonly amplified in LUSC, promoting its growth by maintaining stem cell-like phenotype of cancer cells." (PMID 36973297, 2023).
cancer (continued). "To investigate whether the SRR124–134 cluster drives SOX2 expression in cancer cells, we used CRISPR/Cas9 to delete this cluster from breast (MCF-7, T47D) and lung (H520, PC-9) cancer cell lines." (PMID 37738673, 2023). "Specific surface markers of cancer stem cells, such as the stem cell marker Prominin-1 (CD133), Octamer-binding transcription factor 4 (OCT4), Transcription factor SOX-2 (SOX2), and Homeobox protein NANOG (NANOG), are frequently used for classifying cancer stem cells." (PMID 36769824, 2023). "As a negative control, we measured the correlation between chromatin accessibility at pSOX2 and at the SOX2 desert region and found no significant (P > 0.05) correlation in any of these cancer types." (PMID 37738673, 2023). "Thus, it can be concluded that chemoresistant cells are characterized by the accumulation of cancer stem cells and the increased expression of stemness (CD44, CD133, CD10, ALDH) and pluripotency (NANOG, BMI1, OCT4, SOX2) markers." (PMID 37453969, 2023). "Paracrine HGF induces YAP nuclear translocation by binding c-MET, resulting in the crosstalk between CAFs and cancer cells that HGF/c-MET-mediated induces the expression of stemness pluripotency markers such as NANOG, OCT4, and SOX2 in PC cells, as well as increased self-renewal ability." (PMID 37173787, 2023). "Moreover, 8% of TAp63-/- mice also spontaneously form mammary adenocarcinoma at 9–16 months of age, and TAp63-/- mice have also been shown to express high levels of Sox2 and BMP4, which are known markers for cancer stem cells." (PMID 37182132, 2023). "Recently, special attention has been paid to SRY-box transcription factor 2 (SOX2), which acts not only as a transcriptional target of ASCL1, but also as a prominent transcription factor that promotes pluripotency in embryonic stem cells and cancer stem cells." (PMID 37422534, 2023). "Furthermore, IR induces the re-expression of specific stem cell regulators, such as SOX2, OCT4, Nanog, and KLF4, which promotes stemness in cancer cells." (PMID 38020914, 2023). "In order to compare not only SOX2/SOX9 expression level changes, but also the STING and its related genes activation statues, the single cell RNA sequencing datasets of the reawakened dormant and macrometastatic cancer cells were analyzed." (PMID 38093789, 2023). "Supporting our speculation, RMS patient samples express several pluripotent cancer stem cell markers (CD24, CD133, Oct-4, Sox2, Nanog, and c-Myc) and are able to differentiate into neuronal cells, osteogenic cells, myocytes, and adipocytes." (PMID 37349371, 2023). "Moreover, the expression of SRY-box transcription factor 2 (SOX2), also essential for the self-renewal of cancer stem cells, is found to be governed by IGF2BPs." (PMID 37554271, 2023). "Cancer stem cells harbor the properties of cancer cells and stem cells simultaneously, and several typical stemness factors have been proven to modulate CSC maintenance, including c-Myc, Sox2, and Sox4." (PMID 38933287, 2023). "CAFs and STC1 could upregulate the expression of cancer stemness genes (NANOG, SOX2, and OCT4), and STC1-Ab treatment blocked the promoting effect of CAFs on the expression of stemness genes in HCC cells." (PMID 37004088, 2023). "The C/D box snoRNA SNORD1C was highly expressed in CRC to enhance cancer cell stemness and 5-FU resistance via the Wnt/β-catenin pathway, resulting in downregulation of c-Myc downstream, as well as other stem cell regulatory genes, such as CD44 and SOX2." (PMID 36766788, 2023). "Additionally, other autoantibodies targeting SOX2, HIF1-α, NY-ESO-1/CTAG1B, MUC1, Her2, GAL1, and GAL3 have been frequently identified in cancer patients." (PMID 37627091, 2023). "Our investigations revealed that Dicer silencing was correlated with an increase in the mRNA and protein expression levels of the following cancer stem cell–related transcription factors, as indicated by qRT-PCR and Western blotting: Oct-4, Nanog, KLF4, and SOX2." (PMID 37976135, 2023).
cancer (continued). "Moreover, cancer cell stemness markers OCT4 and SOX2 were detected quantitatively and high levels of SOX2 were found in PFKFB4‐OE MCF‐7 cells compared with normal MCF‐7 cells." (PMID 36127291, 2023). "SOX2 is one of key regulators in HNSCC and takes part in cancer stemness." (PMID 36979661, 2023). "To evaluate the kinetics of cancer stemness changes during the osteogenic and adipogenic inductions, we examined the relative gene expression of the OCT4, SOX2, and NANOG markers in the CD44+ cells at the beginning (0 days), and after 7, 14, and 21 days of differentiation." (PMID 36902135, 2023). "OCT3/4, SOX2, Nanog, and KLF4 are CSC transcription factors that are involved in carcinogenesis and have been used to detect cancer stem cell subpopulations in various types of cancer." (PMID 37070617, 2023). "Therefore, gene expression of cancer and normal stem cells markers CD133, Nanog, Oct4, and Sox2 was analysed in AHH-1 cells in which giant cells were detected." (PMID 37689722, 2023). "Since CSCs are implicated in the growth, migration, invasion, angiogenesis, anti-cancer drug resistance, and metastasis in MIBC, the influence of Chaga on the expression levels of three important CSC markers, CD44, SOX2, and YAP1 which were upregulated in most of MIBC were examined." (PMID 37153767, 2023). "Furthermore, GSK J4 treatment significantly reduces the occupancy of KDM6B on promoters of both SOX2 and CD44, suggesting the KDM6B-driven regulation of these stemness genes in detached cancer cells." (PMID 35186918, 2022). "Moreover, the overexpression of KLF4, SOX2, and NANOG were found in several malignancies, and their expression levels were correlated with poor prognosis, advanced-stage cancer, and shorter patient survival." (PMID 36553636, 2022). "We demonstrated that SES maintains its efficacy to silence the SOX2 target genes that support the proliferative capability and apoptosis resistance of cancer cells, even when SOX2 itself is not expressed." (PMID 35921410, 2022). "Based on the original concept of the embryonal origin of cancer, and thanks to the advent of scRNA-seq technology, we were able to identify a population of GBM cells with concurrent high levels of the core ESC pluripotency factors OCT4, SOX2, and NANOG." (PMID 35565200, 2022). "SOX2-mediated GLI activation is best characterized in SHH-MB, where a SOX2-enriched cancer cell cluster harbors noncanonical GLI activation to render them resistant to SMO inhibition." (PMID 36556332, 2022). "Previous research has shown that HGF stimulates an increase in SOX2 and OCT-4 gene expression in cancer stem cells via the c-MET receptor and affects the maintenance of the stemness of human mesenchymal cells of bone marrow during long term cultures of over eight passages." (PMID 35883581, 2022). "The patient-derived spheroid cultures of TGCT cells that we used in the present study initially exhibit a characteristic of cancer stem-like cells (CSCs) because the model abundantly expressed CSC markers such as NANOG and SOX2, and the TGCT cultures can be easily applied to in vivo models." (PMID 36319719, 2022). "By binding to the promoters of Oct4, Nanog, and Sox2, STAT3 could regulate the gene expression of some cancer stem-like cell markers, which may contribute to carcinogenesis and progression." (PMID 35087591, 2022). "Moreover, focal CNA amplification peaks harbor canonical cancer genes including the HPV-integrated hotspots within MYC family, SOX2, and others." (PMID 36216793, 2022).
cancer (continued). "As happens with non-transformed stem cells, the stemness of cancer cells is regulated by transcription factors like the octamer-binding transcription factor 4 (Oct4), Nanog, and SRY-box 2 (Sox2)." (PMID 36421698, 2022). "Furthermore, by targeting pluripotency factors like OCT4, SOX2, and KLF4 in various cancers, miR-145-5p has been shown to suppress the cancer stem cell-like properties and contribute to chemotherapy and radiation sensitivity." (PMID 35368699, 2022). "We performed qRT-PCR to analyzed the expression of cancer stemness markers and found that the overexpression of miR-200b in the MCF-7/shDicer cells reduced the expression of the stemness markers Oct-4, Nanog, SOX-2, and KLF4." (PMID 35951366, 2022). "They showed minimal cytotoxicity to cells by measuring lactate dehydrogenase (LDH) release from cancer cells to culture media, and had no/low impacts to the expression of Let-7, SOX2 and HMGA2 in DUNE (KO) cells." (PMID 36428779, 2022). "SOX2 has been shown to be expressed in different in cancers, but its expression in ESCC has been not been well-studied." (PMID 36195940, 2022). "In addition, SOX2 expression and O-GlcNAcylation levels in KRAS-activated cancer cells were suppressed by dinaciclib." (PMID 35190631, 2022). "We showed that our identified Lin28 inhibitors have either marginal or no impacts on Let-7d, HMGA2, and SOX2 expressions, highlighting the on-target effects of these inhibitors in cancer cells." (PMID 36428779, 2022). "An increase in the cancer stem cell markers ALDH1A1, SOX2, and NANOG were also observed by PCR." (PMID 35102251, 2022). "Cancer stem cell properties play critical roles in tumorigenesis, progression, and therapy, and SRg3 inhibits self-renewal activity in breast stem-like cancer cells by blocking Akt-induced HIF-1α activation and inhibiting HIF-1α-regulated expression of Bmi-1 and Sox-2." (PMID 36278171, 2022). "Mechanistically, AGXT may sustain the self-renewal potential of LCSCs by upregulating the expression of SRY-box transcription factor 2 (SOX2) and octamer-binding transcription factor 4 (OCT4), two well-known master regulators of cancer stemness." (PMID 35625596, 2022). "Moreover, focal CNA amplifications encompassed genomic peaks that harbored canonical cancer genes including those found at HPV-integrated hotspots (MYC, MYCN, MYCL, SOX2, NR4A2, and ANKRD12), and others (CCNE1, SMAD2, BCL2L1, and GNAS)." (PMID 36216793, 2022). "Similarly, gene expression of other cancer stemness markers NANOG, SOX2, and OCT4 in HepG2 cells was also increased significantly." (PMID 36411463, 2022). "Furthermore, SIRPγhi cancer cells displayed decreased p-MST1, p-LATS1, and p-YAP, and enhanced SOX2 expression compared with SIRPγlo/– cells." (PMID 35229723, 2022). "Indeed, X-ray photon irradiation resulted in an increase in cancer stem cells markers (CD44, CD133, OCT4, SOX2, and NANOG) and increased the pool of cancer stem cells in xenograft mouse models." (PMID 35740495, 2022). "Since stemness markers determine self-renewing cell populations with CSC characteristics in various types of cancers, we next examined the effect of TWIST1 overexpression on the induction of stemness genes SALL4, OCT4, NANOG and SOX2 in KYSE-30 and YM-1 ESCC cells." (PMID 36474162, 2022). "Several lines of evidence have revealed the functional and reciprocal dependencies between SOX2 and the PI3K/AKT signaling pathway which may contribute to cancer metastasis and chemoresistance." (PMID 35309116, 2022). "This suggested that SOX2 expression by cancer epithelia was induced by crosstalk with CAF, rather than secreted factors from these cells." (PMID 35884514, 2022). "Although the roles of Sox2 in stem cells and cancer cells have been clarified in many studies, so far no studies about the possible role of Sox2 in mature or terminally differentiated cells have been reported." (PMID 35227273, 2022).